CXCL1 (C-X-C motif chemokine ligand 1)
Diseases named in the same sentence as CXCL1 in open-access papers (continued):
Sharing a sentence is not in itself a finding about the gene and the disease.
ileus (3 papers, 2021 to 2023). Decrease in peristalsis in the absence of a mechanical bowel obstruction. "We previously showed that the increased cyclical stretch of macrophages, which macrophages would experience in the intestinal wall during the development of edema or ileus, increases the secretion of inflammatory mediators such as CXCL1 and IL-1β." (PMID 37298834, 2023). "However, CXCL1 is upregulated in animal models of ileus and inhibits intestinal contractile activity in mice and rats." (PMID 35805922, 2022). "In addition, CXCL1 was significantly higher in trauma patients who developed ileus compared to trauma patients with no slowed motility." (PMID 35805922, 2022).
invasive breast carcinoma (3 papers, 2014 to 2023). A carcinoma that infiltrates the breast parenchyma. "Mir200 has been shown to modulate CXCL1 mRNA expression in invasive breast cancers." (PMID 25344051, 2014). "This possibility was supported by significant upregulation of IL8 receptors (CXCL1 and CXCL2) in clinical invasive breast cancer samples but not in normal controls." (PMID 28703802, 2017).
keratoconus (3 papers, 2022 to 2024). A degenerative, structural disorder of the eye, characterized by a cone-shaped protrusion of the cornea. "Notably, multiple interleukins (such as IL23A) and chemokines (such as CXCL1) significantly elevated in keratoconus DCs, indicating activated immune response in DCs during keratoconus pathogenesis." (PMID 35821117, 2022).
Lewis lung carcinoma (3 papers, 2016 to 2025). "In mice bearing Lewis lung carcinoma (LLC), hypofractionated RT (8 Gy × 3) induced persistent DNA double-strand breaks, upregulated chemokines such as CXCL1, CXCL2, and CCL5, and recruited newly infiltrating neutrophils into the TME." (PMID 40805288, 2025). "Meanwhile, in the Lewis lung carcinoma (LLC) model, fractionated 8 Gy × 3 RT induced CXCL1/2/5 chemokines and robust ROS production, promoting mesenchymal-to-epithelial transition (MET) and enhancing tumor radiosensitivity." (PMID 40805288, 2025).
liver failure (3 papers, 2015 to 2025). A liver disease characterized by the liver losing or has lost all of its function. "Studies have reported that elevated CXCL1 expression positively correlates with neutrophil infiltration in liver samples from drug-induced liver failure." (PMID 40872846, 2025). "As few patients presented with kidney, respiratory system, or circulatory system failure and most patients exhibited liver failure, it was difficult to identify a correlation between CXCL1 and organ failure in these other systems." (PMID 34395462, 2021). "It is also interesting to note that ADIPOQ, β-NGF, CXCL1, CXCL9, CXCL12, IL-16, and PECAM-1 are up-expressed only in those CHC and HCC patients who present a liver failure, and, hence, linkable to the necro-inflammatory activity of the liver." (PMID 26226632, 2015).
metastatic cancer (3 papers, 2018 to 2023). A carcinoma which has spread from the original site of growth to another anatomic site. "Interestingly, several well-known oncogenes linked to aggressive and metastatic cancer phenotype, including CXCL1, CXCL2, MYC, and BMP4, were included in this gene get, suggesting that BRD4 and STAT3 can coordinately regulate the oncogenic enhancer activity to promote tumor progression." (PMID 34290255, 2021). "The pro-tumour inflammatory effects of CXCL1 in the liver have been systematically explored in secondary liver metastatic cancer." (PMID 37037815, 2023). "Our present findings suggest that CXCL1 from the primary tumor controlled the behavior of metastatic cancer cells in a paracrine manner." (PMID 30123429, 2018).
pneumonitis (3 papers, 2020 to 2025). An inflammatory process affecting the lung parenchyma. "Moreover, we detect biological differences between the two grades of pneumonitis, highlighting the potential value of cytokines such as CXCL-1, CD154, IL-1ra, IL-23, MIF, PAI-1 and IFN-γ as a prognostic marker for developing high grade of lung toxicity." (PMID 33109238, 2020). "Previous studies have reported that fibrogenic cytokines including CXCL1, CXCL2, TNF-α, and CXCL8 are involved in bleomycin-induced pneumonitis." (PMID 41425704, 2025).
prostate adenocarcinoma (3 papers, 2016 to 2022). "After analyzing human prostate adenocarcinomas in The Cancer Genome Atlas (TCGA) Program, the IL1RN was indeed tightly correlated with both CCL2 and CXCL1." (PMID 33322099, 2020). "Among them, IL-1β, IL-6, and CXCL1 have been reported to be factors of immune suppressive SASP that attract myeloid-derived suppressor cells (MDSCs) to inhibit cytotoxic NK and T cell responses in prostate adenocarcinoma." (PMID 36330438, 2022).
pulmonary TB (3 papers, 2021 to 2023). "CXCL1 can be considered a marker of pulmonary tuberculosis, distinguishing it from latent infection." (PMID 36613652, 2022). "Blood CXCL1 levels are elevated in patients with pulmonary tuberculosis and these levels correlate with bacterial burdens." (PMID 36613652, 2022). "Using Area Under the Curve analyses, CXCL1 averaged 94.5% sensitivity and 88.8% specificity for active pulmonary TB (ATB) vs LTBI; 90.9% sensitivity and 71.4% specificity for ATB vs non-TB; and 100.0% sensitivity and 98.4% specificity for ATB vs normal sera." (PMID 34403447, 2021). "AUC, sensitivity, and specificity values of CXCL1, MMP8, and S100A8 are given for active pulmonary TB (ATB) vs pooled normal, ATB vs latent Mtb infection (LTBI) infection, and ATB vs non-TB comparisons." (PMID 34403447, 2021). "Similarly, an earlier study has shown that treatment with a PDE4i such as roflumilast and rolipram controlled the neutrophil recruitment by reducing TNF-α, IL-6, CXCL1, and CXCL2/3 in a rabbit model of pulmonary TB." (PMID 37854602, 2023).
rectal cancer (3 papers, 2021 to 2025). A primary or metastatic malignant neoplasm that affects the rectum. "It has been found that has-miR-1-3p could be involved in the progression of rectal cancer by regulating CXCL1, CXCL2, and CXCL3." (PMID 34269159, 2021). "The fact that has-miR-1-3p targets three hub genes simultaneously (FDR <0.05) indicated that has-miR-1-3p could be involved in the progression of rectal cancer by regulating CXCL1, CXCL2, and CXCL3." (PMID 34269159, 2021). "In our study, we contend that has-miR-1-3p may affect the prognosis of rectal cancer by targeting CXCL1, CXCL2, and CXCL3." (PMID 34269159, 2021). "Seven hub genes, including SAA1, AGT, GNG4, GAL, CXCL1, CXCL2, and CXCL3, were upregulated in rectal cancer tissues." (PMID 34269159, 2021). "CXCL1 and CXCL3, which were selected carefully from the GEO database, were the independent prognosis factors for rectal cancer." (PMID 34269159, 2021). "Besides CXCL1, CXCL2, and CXCL3, we mined seven other hub genes related to rectal cancer, including SAA1, AGT, GNG4, SST, SSTR2, GAL, and CXCL12." (PMID 34269159, 2021). "Results from a variety of bioinformatics analyses suggest that hub genes (CXCL1, CXCL2, and CXCL3) could be significant biomarkers for the prognosis of rectal cancer." (PMID 34269159, 2021). "Therefore, CXCL1 and CXCL3 may be involved in the progression of rectal cancer under the regulation of related macrophages." (PMID 34269159, 2021).
retinal degeneration (3 papers, 2017 to 2025). Degeneration of the retina. "Several of these chemokines, including CCL2, CXCL1 and CXCL10 are involved in leukocyte recruitment in CNS diseases and in retinal degeneration." (PMID 28438165, 2017).
rosacea (3 papers, 2022 to 2025). A chronic erythematous skin disorder that affects the face. "Moreover, EGCG also reduced the expressions of the neutrophil-attracting chemokines (Cxcl15 and Cxcl1), macrophage markers (Cd68 and Itgam), and mast cell-related genes (Tpsab1 and Cma1) in LL-37-induced rosacea-like lesions." (PMID 36937834, 2023). "Research has demonstrated that CXCL8, CXCL1, and CXCL2 are significantly upregulated in patients with rosacea." (PMID 41431076, 2025). "TNF-α and IL-1β are known to induce the expression of a subset of proinflammatory chemokines (CXCL1, CXCL8, CCL20, and CCL27) in keratinocytes, implying a potential pathway for TH1 and TH17 cell recruitment as well as neutrophil recruitment in rosacea lesional skin." (PMID 35832851, 2022).
systemic inflammatory response syndrome (3 papers, 2020 to 2022). SIRS is a serious condition related to systemic inflammation, organ dysfunction, and organ failure. "Similar trends were observed with IL-1β and CXCL-1, suggesting a decreased likelihood of progression to a systemic inflammatory response syndrome-like state." (PMID 35465347, 2022). "Specifically, we found of significant elevation of the inflammatory cytokines IL-1β, TNF-α, IL-6, and CXCL1 in the peripheral circulation at P10, around human term age equivalent, in POE rats suggesting a systemic inflammatory response syndrome (SIRS)-like response." (PMID 37396628, 2022).
Thrombocytopenia (3 papers, 2017 to 2024). A reduction in the number of circulating thrombocytes. "The DENV-induced thrombocytopenia caused by impaired thrombopoiesis and peripheral destruction of platelets may explain the reduced CXCL1 serum levels since platelets represent a source of this chemokine." (PMID 28586397, 2017). "PLAG significantly decreased plasma levels of the chemokine (C–X–C motif) ligand 1 (CXCL1), CXCL2, interleukin (IL)-6, and C-reactive protein (CRP), which were elevated consistently with the occurrence time of neutropenia, monocytopenia, and thrombocytopenia." (PMID 31752148, 2019).
vasculitis (3 papers, 2018 to 2023). "Thus, decreasing the production of CXCL1 and IL-8 in the inflamed vascular walls of CAWS-induced vasculitis by inhibiting LPA1 may also contribute to the suppression of neutrophil infiltration in vivo." (PMID 31429784, 2019).
abdominal aortic aneurysm (2 papers, 2024). Enlargement and ballooning of the vessel that supplies arterial blood to the abdomen, pelvis and legs. "Bioinformatics and immune cell infiltration analysis have revealed that CXCL1-mediated neutrophil activation is a shared immune-inflammatory regulatory mechanism in abdominal aortic aneurysm (AAA) and SLE." (PMID 39421304, 2024). "We obtained six macrophage hub genes (IL-1B, CXCL1, SOCS3, SLC2A3, G0S2, and CCL3) that can effectively diagnose abdominal aortic aneurysm." (PMID 38867262, 2024).
acute lung injury (2 papers, 2016 to 2021). A condition of lung damage that is characterized by bilateral pulmonary infiltrates (pulmonary edema) rich in neutrophils, and in the absence of clinical heart failure. "Recent studies showed that CXCR2 (the receptor of CXCL1 and CXCL2) blockade results in impaired neutrophil recruitment in lipopolysaccharide-induced acute lung injury." (PMID 27447715, 2016).
acute-on-chronic liver failure (2 papers, 2021 to 2025). Acute-on-chronic liver failure (ACLF) is an extreme condition during the natural history of chronic HBV infection, with a relatively high short-term mortality. "As an example, a recent study on HBV-related acute-on-chronic liver failure (ACLF) found that another CXC chemokine, which was CXCL1, predicted 28-day mortality almost as well as MELD (AUC 0.74 vs. 0.75)." (PMID 41373861, 2025).
alcoholic liver diseases (2 papers, 2013 to 2022). A disorder caused by damage to the liver parenchyma due to alcohol consumption. "Sera from alcoholic patients, but not from healthy controls, were able to stimulate TLR2- and TLR4-transfected HEK293 cells to secrete CXCL1, suggesting that CXCL1 up-regulation is dependent on soluble factors found in alcoholic liver disease, and involves TLR2 and TLR4 signaling." (PMID 24260493, 2013).
anaphylaxis (2 papers, 2022 to 2025). An acute hypersensitivity reaction that occurs from exposure to an allergen. "IL-4 signaling might increase CXCL1 expression to mediate allergic inflammations such as anaphylaxis." (PMID 40005151, 2025). "In addition, the selective elevation of IL-6 and a small panel of chemokines (CCL5, CCL20, CCL22, and CXCL1) in the spleen upon oral allergen but not saline challenge suggests their key role in eliciting anaphylaxis via the oral route." (PMID 36238931, 2022).
anemia (2 papers, 2012 to 2020). A reduction in the number of red blood cells, the amount of hemoglobin, and/or the volume of packed red blood cells. "We observed that the combination of anemia and LPS administration resulted in higher plasma levels of the inflammatory markers IL-6 and CXCL1/KC than did either challenge alone." (PMID 22919395, 2012). "Indeed, AA and ferric maltol (approved for the treatment of iron-deficiency anemia in IBD31) triggered epithelial LPO, Cxcl1 expression and small intestinal neutrophilic infiltration in Gpx4+/−IEC mice." (PMID 32286299, 2020). "Acute anemia or lipopolysaccharide (LPS) challenge alone triggered an increase of circulating levels of the inflammatory markers IL-6 and keratinocyte-derived chemokine (CXCL1/KC)." (PMID 22919395, 2012).
autoimmune myocarditis (2 papers, 2014 to 2018). Autoimmune myocarditis is an autoimmune disease that affects the heart. "We report here that CXCL1/KC production is TLR4 dependent in the context of autoimmune myocarditis." (PMID 24586934, 2014).
bacteremia (2 papers, 2025). "Children with unexplained fever and high CRP had a gene expression profile distinct from those with bacteremia, including downregulated CXCL1, MYOZ3, and HSPG2." (PMID 40806258, 2025). "While elevated CXCL1 has been previously associated with S. aureus bloodstream infection, its role in development of persistent MRSA bacteremia has not been previously studied." (PMID 39966757, 2025).
bladder overactivity (2 papers, 2013 to 2025). "Using the urine chemokines CXCL-1 and IL-8, we can discriminate overactive bladder symptoms between DO and urinary tract infection in women." (PMID 40002782, 2025). "The oxidative stress markers and proinflammatory cytokines including IL-8-like cytokine CXCL1/CINC-1, TNF-α, and IL-6 were significantly higher in the atherosclerotic ischemic rats; these markers could be key factors in the development of bladder overactivity." (PMID 24098552, 2013).
Bovine mastitis (2 papers, 2020 to 2025). INFLAMMATION of the UDDER in cows. "Cxcl-1 chemoattracts leukocytes to sites of infection; recruitment of neutrophils and monocytes/macrophages from blood to milk compartments is a critical defense mechanism in bovine mastitis." (PMID 32117805, 2020).
Cachexia (2 papers, 2023 to 2025). Severe weight loss, wasting of muscle, loss of appetite, and general debility related to a chronic disease. "When we performed a linear model with either ENA-78/CXCL5 or GRO-α as response variables and R&E, cachexia status, stage, sex, and BMI as predictor variables, NHB demonstrated significantly increased ENA-78/CXCL5 and GRO-α/CXCL1 compared to other R&E groups." (PMID 39989973, 2025). "Further stratification by cachexia status for ENA-78/CXCL5, GRO-α /CXCL1 and GDF-15 (as a comparison) shows that ENA-78/CXCL5 and GRO-α/CXCL1 levels were unchanged for any R&E group when stratified by cachexia status." (PMID 39989973, 2025).
Carditis (2 papers, 2013 to 2020). "In fact, Cxcl1 mediates the recruitment of neutrophils and subsequent swelling in Lyme arthritis and carditis." (PMID 32645014, 2020). "The interaction between CXCL1 and CXCR2 is critical for mediating leukocyte recruitment in many diseases such as Lyme Arthritis, Carditis and experimental brain abscesses." (PMID 23967336, 2013).
cholestasis (2 papers, 2020 to 2022). Impairment of the bile flow caused by obstruction within the liver, or outside the liver in the bile duct system. "Various molecules such as CCL2, CXCL1, CXCL2, and ICAM-1 have been reported to be important in neutrophil trafficking in the liver, which explains why liver injury occurs during cholestasis." (PMID 32701506, 2020).
chronic rhinosinusitis (2 papers, 2016 to 2022). Chronic form of sinusitis. "Neutrophils in chronic rhinosinusitis are recruited to the nasal mucosa by CXCL1." (PMID 36613652, 2022).
clear cell renal cell carcinoma (2 papers, 2021 to 2023). "In addition, there was a correlation between CXCL1/2/3/8 and neutrophils in renal clear cell carcinoma." (PMID 37540227, 2023).
colon adenoma (2 papers, 2015). An adenoma that arises from the colon. "Notably, elevated CXCL1 levels occurred early in 77% of colon adenomas and were sustained at high levels throughout 81–94% of primary stage I–IV CRC." (PMID 26104296, 2015). "No CXCL1 ISH signal was detected in normal colon and in the colon adenomas." (PMID 26208990, 2015).
colonic diseases (2 papers, 2025). "Summarizing these results, we identified 5 proteins (CCL20, CXCL1, CXCL11, HGF, and IL-24) with increased abundance in colonic diseases, irrespective of the disease entity (colonic CD and UC) that significantly correlated with both, tissue gene expression and inflammatory severity." (PMID 40291692, 2025).
cryptococcal infections (2 papers, 2025). "Both CXCL1/KC and CXCL2/MIP-2α have been observed in cryptococcal infections." (PMID 40666971, 2025). "Additionally, both CXCL1/KC and CXCL2/MIP-2α have been observed in cryptococcal infections." (PMID 41357248, 2025).
demyelinating disease (2 papers, 2021 to 2024). A broad group of disorders that affect the myelin sheaths that cover the neurons. "Since CXCL1 has been implicated in many neuroinflammatory disorders and their models, such as EAE, MS, other demyelinating diseases, neurodegeneration, and infection, being able to modulate its secretion at one of its sources may be a common solution to seemingly unrelated pathologies." (PMID 38534751, 2024). "In contrast to CCL2, both the lack of CXCL1 during TMEV infection and the excessive presence of this chemokine promote the pathogenesis of demyelinating disease." (PMID 34067536, 2021).
disc degeneration (2 papers, 2014 to 2025). "A bioinformatic investigation revealed that the CXCL-1 gene may be involved in the pathogenesis of disc degeneration caused by an inflammatory response." (PMID 41153707, 2025).
Ductal Carcinoma in Situ (2 papers, 2014 to 2023). "Using immunohistochemistry approaches, we first analyzed CXCL1 protein expression patterns in tissues from normal tissues, pre-invasive lesions known as Ductal Carcinoma in Situ (DCIS), and IDC tissues." (PMID 25344051, 2014).
Erythema (2 papers, 2023 to 2025). Redness of the skin, caused by hyperemia of the capillaries in the lower layers of the skin. "In addition, 7-methoxyisoflavone has been reported to significantly suppress CXCL1, CXCL2, and CXCL3 expression in both FITC- and oxazolone-induced AD models, which was associated with reduced neutrophil infiltration and attenuated skin erythema and edema." (PMID 40918538, 2025). "We analyzed the correlation between the values of IL-1α, IL-1RA, CXCL-1/2, and hBD-1 measurements from psoriatic skin against the PASI and the values of erythema, induration, and desquamation, at the area of the FibroTx TAP measurements." (PMID 36936209, 2023). "Among them, C-X-C motif chemokine ligand 1 and 2 (CXCL1 and CXCL2) are significantly upregulated in lesional skin and primarily mediate neutrophil recruitment through interaction with the CXCR2 receptor, thereby aggravating tissue damage and acute symptoms such as erythema and edema." (PMID 40918538, 2025).
fibromyalgia (2 papers, 2018 to 2020). A chronic disorder of unknown etiology characterized by pain, stiffness, and tenderness in the muscles of neck, shoulders, back, hips, arms, and legs. "Interestingly, increased CXCL1 production by neutrophils has been seen in patients with fibromyalgia, however, considering the small numbers within the studies, these findings should be considered exploratory and further investigation is required to define their clinical implications." (PMID 29426834, 2018).